APOA2 (apolipoprotein A2)
Diseases named in the same sentence as APOA2 in open-access papers (continued):
Sharing a sentence is not in itself a finding about the gene and the disease.
cardiovascular disease (8 papers, 2012 to 2025). "Notably, the most prominent associated proteins were APOA1 and APOA2, crucial components of HDL and widely recognized as protective markers for cardiovascular disease." (PMID 40926231, 2025). "However, the impact of ApoA2 in cardiovascular disease is controversial." (PMID 38732018, 2024).
infection (8 papers, 2013 to 2023). The state of being infected such as from the introduction of a foreign agent such as serum, vaccine, antigenic substance or organism. "Infection of cells with the Lefty1, Pcp4l1, and Apoa2 encoding viruses increased BrdU incorporation by 87%, 80%, and 92%, respectively; overexpression of Ifi202b decreased the number of BrdU positive cells by 43%." (PMID 26348837, 2015). "As seen in infection with HCVcc (JFH1), expression of ApoA1, ApoA2, ApoC1, ApoC2, ApoC3 and ApoE enhanced the formation of infectious particles of TH/JFH1 and S310/JFH1 chimeric viruses." (PMID 25502789, 2014). "The proteins altered during the infection and maintained altered also after recovery enriched functions related to cholesterol transport and metabolism, including APOL1, APOA2, and SERPINA12 for moderate patients, and APOA5, APOL1, APOA2, and CSE1 for severe ones." (PMID 35269564, 2022).
metabolic disease (2 papers, 2020 to 2022). A congenital disorder (due to inherited enzyme abnormality) or acquired (due to failure of a metabolically important organ) disorder resulting from an abnormal metabolic process. "Afamin, ApoA4 and ApoA2 have previously been reported to be linked to the development of metabolic disease including one or more of T2D, DKD, or NASH as detailed below." (PMID 32830851, 2020).
APOA2 also shares sentences with these, for which no sentence is quoted: dyslipidemia (10 papers); Alzheimer disease (3); brain tumor (3); chronic kidney disease (3); coronary atherosclerosis (3); dementia (3); multiple myeloma (3); pancreatic ductal adenocarcinoma (3); asthma (2); Atrophy (2); colorectal cancer (2); endometriosis (2); glioma (2); heart failure (2); malnutrition (2); multiple sclerosis (2); non-small cell lung carcinoma (2); Aapoaii Amyloidosis (1); acne (1); acute myeloid leukemia (1); acute pancreatitis (1); acute-on-chronic liver failure (1); anemia (1); Anxiety (1); Atherosclerotic lesion (1); atopic dermatitis (1); cholangiocarcinoma (1); Cholestatic liver disease (1); chronic hepatitis B (1); chronic tubulo-interstitial nephritis (1).
A further 58 diseases each share a sentence with APOA2 in 1 paper.